KRAS (KRas proto-oncogene, GTPase)
Diseases named in the same sentence as KRAS in open-access papers (continued):
Sharing a sentence is not in itself a finding about the gene and the disease.
colon carcinoma (continued). "Patient 2 had a primary diagnosis of stage III RAS mutant colon cancer (KRAS G12C), with evidence of liver metastasis six months after the diagnosis." (PMID 30621206, 2019). "Nevertheless, ctDNA for KRAS G13D remained high (7 c/ml) suggesting possible radiologically undetectable progression of the patient’s untreated colon cancer." (PMID 31727009, 2019). "Apart from KRAS status, and resistance to anti-EGFR therapy, mutations in PIK3CA are associated with proximal colonic tumors, and adverse outcomes for patients with BRAF wild-type tumors." (PMID 30736475, 2019). "In conclusion, our study identified β-catenin signalling as an important factor in MEK inhibitor resistance in KRAS mutant colon cancers." (PMID 30944457, 2019). "With this in mind, Sinicrope and colleagues identified two subtypes of colon cancer deficient in mismatch repair based on mismatch repair status and detection of B-Raf Proto-Oncogene (BRAF) V600E or mutations in KRAS Proto-Oncogene (KRAS)." (PMID 31390840, 2019). "We investigated a biomarker of response for MEK inhibition in KRAS mutant colon cancers by LC-MS/MS analysis." (PMID 30944457, 2019). "Four studies with 6697 patients provided the survival data of KRAS status in colon cancer, with 3670 LCC patients and 3027 RCC patients, respectively." (PMID 30917791, 2019). "As a consequence, combination of KRAS inhibition and trametinib effectively suppressed the viability of KRAS mutant colon cancer cells in vitro and in vivo." (PMID 30833665, 2019). "Here we show that TNTs mediate intercellular transfer of mutant KRAS in recipient colon cancer cells, thus facilitating intracellular and molecular heterogeneity in the tumor microenvironment." (PMID 31247990, 2019). "For example in colon cancer, the KRAS mutation was found 22-39% and the BRAF mutation was found 2.8-6.6% While, the KRAS and BRAF mutations in mucinous ovarian cancer were 50-75% and 3.5% respectively." (PMID 31030485, 2019). "All these data reinforce the notion that B-RAF and KRAS-driven colon cancer cells are “addicted to autophagy” and indicate, therefore, that HIFs factors play essential roles in regulating cell death pathways to promote cell survival." (PMID 31151160, 2019). "In the present study, it is demonstrated that KRAS and BRAF mutations induce anoikis resistance in colon cancer (Caco-2) cells." (PMID 31545494, 2019). "Like KRAS in colon cancers, HRAS increases intracellular O2•− levels by activating membrane-associated NOXs in human lung cells." (PMID 31288436, 2019). "Several studies have shown that the majority of MEK inhibitor-insensitive colon cancer cell lines harbour activating mutations in the PI3K pathway, whereas KRAS mutant cancer cells with an intact wild-type PI3K pathway are sensitive to MEK inhibitors." (PMID 30944457, 2019). "Optimized siRNAs targeting KRAS impaired colon cancer growth in vivo while combinatorial inhibition of KRAS and PIK3CA/PIK3CB significantly improved tumor control compared to single agents alone, demonstrating that targets can be effectively multiplexed." (PMID 31681559, 2019). "We demonstrated that targeting KRAS is a promising strategy for treating colon cancer, especially in KRAS-mutant and cetuximab-resistant types." (PMID 31717759, 2019). "KRAS-mediated overexpression of ASNS has been also described in colon cancer in the context of adaptation to nutritional stress upon Gln starvation." (PMID 31998641, 2019). "These agents continue to be investigated in KRAS mutant colon cancer but are met with significant resistance." (PMID 30944457, 2019). "This pathway can be targeted with TAK1 kinase inhibitors, which selectively ablate KRAS-mutant colon cancer xenografts." (PMID 31681559, 2019). "Several recent clinical trials, carried out on large sets of colon carcinoma patients, have assessed the impact of MMR status and BRAF/KRAS mutations on outcome." (PMID 29652830, 2018).
colon carcinoma (continued). "We used the KRAS-dependent metastatic colorectal cancer cell line LoVo, the KRAS-independent colon carcinoma cell line HCT116 and the normal colon cell line CCD-18Co as control." (PMID 30382908, 2018). "The observed cytotoxic effect prompted us to investigate how C19 inhibits viability and proliferation of KRAS-dependent colon cancer cells." (PMID 30382908, 2018). "In 450 stage I to III colon cancers, PIK3CA mutation was associated with a significant increase in colon cancer–specific mortality in the KRAS wt patients." (PMID 29666387, 2018). "Genetic markers were selected to represent the pathways most frequently altered in colon cancer, such as the WNT-pathway (surrogate marker osteopontin), mutations in the oncogenes KRAS and BRAF, and the DNA microsatellite status." (PMID 30340556, 2018). "Our results suggest that overexpression of OPN promote colon cancer cell migration and invasion, and anchorage‐independent growth significantly in the presence of mutant KRAS and to a lesser extent in the wild‐type KRAS counterpart." (PMID 29851214, 2018). "Our data reveal that β-phenylacrylic acid derivatives, MHYs, function as novel EGFR inhibitors in KRAS wild-type colon cancer." (PMID 30158525, 2018). "The three human RAS genes (KRAS, NRAS and HRAS) are the most frequently mutated oncogenes in human cancer appearing in 90% of pancreatic, 35% of lung and in 45% of colon cancers." (PMID 29534749, 2018). "It is known that various preclinical and therapeutic strategies using trametinib combined with another target drug in BRAF/KRAS mutant colon cancers were developed." (PMID 30185207, 2018). "Here we report the development of novel EGFR inhibitors, having pro-apoptotic and tumor suppressive effects in wild-type KRAS colon cancer." (PMID 30158525, 2018). "We identify the ERN1-JNK-JUN pathway as a novel regulator of MEK inhibitor response in KRAS mutant colon cancer." (PMID 30482246, 2018). "In colon cancer cell lines, overexpression of these miRNAs down-regulates KRAS, RREB1 and other genes in the MAPK cascade, which abrogate signalling through MAPK, PI3K and JNK pathways." (PMID 29360852, 2018). "We have exemplified our findings with KRAS-positive colon cancer cells, Myc-amplified neuroblastoma (N-Myc-driven) and confirmed sensitivity of combination therapy in B cell lineage (C-Myc-driven)." (PMID 30318510, 2018). "To investigate how ERN1 modulates MEK inhibitor responses, we performed genetic screens in ERN1 knockout KRAS mutant colon cancer cells to identify genes whose inactivation confers resistance to MEK inhibition." (PMID 30482246, 2018). "KRAS and PIK3CA were the only mutated genes showing differences according to the tumor location, mainly for right colon cancers." (PMID 29632645, 2018). "Second, we used a genome-wide CRISPR/Cas9-based genetic screen in KRAS mutant human colon cancer cells to understand the mechanistic connection between the synthetic lethal interaction discovered in yeast and downstream RAS signaling in human cells." (PMID 30482246, 2018). "In this study, we investigated the role of OPN overexpression related to phenotypic changes using KRAS mutant and KRAS wild‐type colon cancer cells." (PMID 29851214, 2018). "When analyzing the mutation rates of KRAS, NRAS, and BRAF in different locations, it can be found that KRAS gene mutation rate was significantly different in colon cancers (44.2%), rectal cancers (37.1%) and gastric cancers (0%) (p < 0.001)." (PMID 30416987, 2018). "We identify the ERN1-JNK-JUN pathway as a novel regulator of MEK inhibitor response in KRAS mutant colon cancer, and point to synthetic lethality of MEK inhibition with therapeutics targeting JUN activating kinases, TAK1 and JNK." (PMID 30482246, 2018).
colon carcinoma (continued). "A recent study on Chinese patients showed that among KRAS, BRAF, PIK3CA and NRAS mutations in stage II to III colon cancers (n = 228), only PIK3CA mutations were an independent prognostic biomarker for poor OS among stage III patients." (PMID 29666387, 2018). "In these KRAS-dependent colon cancer cells, KRAS activates bone morphogenetic protein 7 (BMP-7) signaling, leading to TAK1 activation, β-catenin nuclear localization and transcriptional upregulation of Wnt target genes." (PMID 29652830, 2018). "Recently, researchers found that TAK1 inhibition induces apoptosis in KRAS-dependent colon cancers and promotes NF-κB-dependent cell death in AML cells in vitro and in vivo." (PMID 29915207, 2018). "In summary, novel β-phenylacrylic acid derivatives have been shown to target KRAS wild-type colon cancer by inhibiting EGFR as well as generating stress responses." (PMID 30158525, 2018). "For example, some researchers confirmed that the overexpression of miR-143 (ranked first in the WINMDA forecast list) reduces cell proliferation and migration of mutant KRAS HCT116 colon cancer cells." (PMID 30597923, 2018). "CD133 mRNA expression, but not that of other cancer stem cell markers, predicted relapse-free survival in colon cancer patients; interestingly, CD133 expression was related to mutations in KRAS and BRAF." (PMID 29652830, 2018). "More recently, Jass and coworkers proposed a classification of colon cancer based on five main criteria: CIN; MSI; CIMP, methylation status of 0–6-island methylguanine DNA Methyltransferase (MGMT); mutational status of KRAS and of BRAF." (PMID 29652830, 2018). "Sequencing studies of KRAS are routinely performed in colon cancer patients undergoing systemic therapy as they are a contraindication to EGFR targeted therapy." (PMID 29698444, 2018). "In a study of 450 patients with stage I to III colon cancer, for example, PIK3CA mutations predicted a poorer prognosis, but only among KRAS wild-type CRC patients." (PMID 29666387, 2018). "To answer this question, we tested the effects of Gamitrinib and 6-thio-dG in KRAS-mutant lung and colon cancer cell lines as well as NRAS-mutant glioblastoma cells." (PMID 29695835, 2018). "A number of preclinical therapeutic strategies have been developed by combining EGFR pathway inhibitors with other target drugs in BRAF/KRAS mutant colon cancers." (PMID 30185207, 2018). "Together, these data suggest that MHYs inhibit EGFR-mediated signaling pathways in colon cancer cells expressing wild type KRAS." (PMID 30158525, 2018). "Nevertheless, the limitations of this study are 1) small sample size especially in colon cancer array and 2) only CD166 was examined and 3) only KRAS exon 2 mutations were examined." (PMID 29755662, 2018). "SW1116, a KRAS-wild-type colon cancer cell line, was transfected with control miRNA, miR-17 or miR-145." (PMID 29459716, 2018). "In mammalian KRAS mutant colon cancer, we find that inhibition of MEK kinases is synthetic lethal with inhibition of the UPR." (PMID 30482246, 2018). "Some studies have suggested that KRAS and BRAF mutations are more frequent among colon than rectum tumors, while the chromosomal instability network is more common in rectal than in colon cancer." (PMID 29652830, 2018). "Taken together, our findings identify an unexpected role for the Unfolded Protein Response executor ERN1 in determining the response to MEK inhibition in KRAS-driven colon cancer." (PMID 30482246, 2018). "Specifically the molecular testing was performed for the EGFR and KRAS mutational analysis based on the previous or contemporary diagnoses of Non Small Cell Lung Cancer (NSCLC) and colon carcinomas." (PMID 28099523, 2017). "miR-155 is positively regulated by CBX7 in MEFs and colon carcinomas, and has KRAS as one of the target genes likely accounting for the anti-apoptotic activity ascribed to miR-155 in some tissue contexts." (PMID 28259135, 2017).
colon carcinoma (continued). "For colon cancer, surgical resection is the most common treatment, so pathology reports also contain clinically relevant search terms that can distinguish KRAS mutants and wild-type genotypes." (PMID 28869500, 2017). "This is concordant with prior investigations indicating a dependence of heat shock protein expression in CRC on KRAS mutation and PI3K activation at least in colon cancer cell lines." (PMID 29029497, 2017). "In the remaining single discordant sample (a colon cancer), a NRAS c.182A>G variant (38% TST variant allele frequency, VAF) was detected by all methods, with an additional c.35G>C KRAS variant called by the prior clinical real-time PCR method." (PMID 28415793, 2017). "Given the high activity of VLX50 and VLX60 against the colon cancer cell line HCT116, which is KRAS mutated, the activity of these drugs was compared in three pairs of colon cancer cell lines with different KRAS and BRAF mutation status." (PMID 28415818, 2017). "The present study was designed to detect the potency of aspirin therapy in colon cancer cell lines according to major somatic driver mutations such as PIK3CA, BRAF, and KRAS mutations." (PMID 29152088, 2017). "In this study, we demonstrated that the combination treatment of TAS‐102 and panitumumab exerted significant anticancer activity compared to that achieved by single‐agent treatment in in vitro and in vivo wild‐type KRAS colon cancer models." (PMID 28486761, 2017). "This last result is in agreement with previous data showing that the MEK inhibitor semulatenib induces HER3 transcriptional up-regulation and phosphorylation in vivo in KRAS mutant lung and colon cancers." (PMID 29312543, 2017). "For instance, in colon cancer cells with a mutant KRAS gene CD95 primarily promotes invasion and metastasis." (PMID 28300842, 2017). "By using KRAS mutant lung, breast and colon cancer cell lines that were rendered resistant to the purine analog PU-H71, we identified two genetic alterations that allowed adaptation to HSP90 inhibition." (PMID 28032595, 2017). "Inhibition of SIRT2 expression also confers resistance to targeted therapies in KRAS-mutant colon cancers." (PMID 28514749, 2017). "Our current study combined the antitumor monoclonal antibody drug, cetuximab, and the functional food, PBR extract, to act synergistically against KRAS-mutant colon cancer cells." (PMID 28800074, 2017). "For example, mutations in the KRAS gene are associated with resistance to anti-EGFR drugs, which are approved selectively for colon cancer patients with wild type (WT) KRAS." (PMID 28420162, 2017). "The combination of the eiF4A inhibitor Episilvestrol and Bortezomib potentiates the killing of a wide variety of colon cancer cells with mutant KRAS/BRAF." (PMID 28030835, 2017). "A random selection of 599 patients with colon cancer were analyzed, selected from the Eindhoven Cancer Registry, and BRAF and KRAS mutation status was determined." (PMID 28125730, 2017). "We observed that Sorafenib inhibited AKT activity only in CaCO2 colon carcinoma cells that are BRAF and KRAS wildtype, and led to an increase in AKT activity in the other cell lines, which had mutations in either KRAS or BRAF." (PMID 26799289, 2016). "Initial stratification of stage I colon carcinomas based on either LGR5 or KRAS status showed activation of the EMT program in those with LGR5− or KRASwt status." (PMID 26744320, 2016). "Next, we stratified the stage I colon carcinomas according to their KRAS status and found that KRASmut (n = 7) instead of KRASwt (n = 10) was associated significantly with the embryonic SC-like signature, but not the intestinal SC signature." (PMID 26744320, 2016). "Tumor specific EGFR downstream signaling mutations in KRAS, BRAF, PTEN, and PIK3CA cause reduced benefit of cetuximab therapy in colon carcinoma patients." (PMID 27100871, 2016).
colon carcinoma (continued). "For example, colon cancer cells expressing an activated mutant form of KRAS have been shown to generate exosomes that are capable of enhancing the anchorage-independent growth and invasive activity of other colon cancer cell lines." (PMID 27941677, 2016). "By the result of the expression of KRAS and XPi2 in 31 colon cancer cases, it was revealed that XPi2 potentially interacted with the KRAS gene in the 31 colon and nearby tissues." (PMID 27880931, 2016). "APC mutations were associated with poor prognosis in (5-fluorouracil treated) stage III colon cancers (p = 0.005; HR = 4.1), an effect that was further enhanced by mutations in MAPK pathway (KRAS, NRAS, BRAF) genes." (PMID 27729614, 2016). "Anti-EGFR therapy in patients with KRAS WT colon tumors is standard of care, whereas patients with RAS mutant tumors are excluded." (PMID 27845624, 2016). "Clinical trial has been established in stage III colon cancer patients to study the anticancer effect by altering the binding capability of miRNA lethal-7 to Kirsten rat sarcoma viral oncogene homolog (KRAS) gene." (PMID 27073801, 2016). "In colon cancer cells, 5-FU exposure impaired endogenous KRAS/MEK5/ERK5 expression and/or activation." (PMID 27144434, 2016). "We further ascertained if the role of miR-143 or miR-145 on increasing cetuximab sensitivity also occurs in KRAS wild-type SW48 colon cancer cells, which are sensitive to cetuximab." (PMID 26824186, 2016). "The authors thank Bert Vogelstein (Howard Hughes Medical Institute, Johns Hopkins University) and Alberto Bardelli (University of Torino, Italy) for isogenic BRAF and KRAS colon cancer cell lines." (PMID 27351224, 2016). "SW48 cells (human colon cancer cell line containing WT KRAS) in PBS or PBS containing WSTF/NRG3 proteins (PBS+) were injected into 6- to 8-week-old female BALB/C mice." (PMID 27449290, 2016). "We analyzed the expression of KRAS and XPi2 in 31-colon cancer cases to determine their roles in the molecular pathogenesis of human colon cancer." (PMID 27880931, 2016). "Statistical analysis indicated a significant correlation between KRAS, XPi2, and colon cancer in the normal and tumor tissues." (PMID 27880931, 2016). "In this report, we have presented evidence that colon cancer cells with mutations in BRAF are also resistant to HSP90 inhibitors, including AUY922 that is currently in clinical trials for the treatment of wild-type KRAS colon cancers." (PMID 27391062, 2016). "Here, we tested the effect of restoring these miRNAs on sensitization to cetuximab in mutant KRAS (HCT116 and SW480) and wild-type KRAS (SW48) colon cancer cells." (PMID 26824186, 2016). "In colon cancer, the efficacy of cetuximab was increased in patients who carried wild-type KRAS; patients who carried the mutant KRAS were resistant to cetuximab treatment." (PMID 26728266, 2016). "We have previously shown that the HSP90 inhibitor AUY922 preferentially induces apoptosis in colon cancer cells carrying mutant KRAS." (PMID 27391062, 2016). "Similar percentages of mutations (40-50%) are found in KRAS and BRAF and 17% of PIK3CA mutations have been determined in colon carcinoma patients." (PMID 25885658, 2015). "The effects of compounds on KRAS transcription in colon cancer cells (HCT116 and SW620) were evaluated by quantifying KRAS mRNA steady-state levels using Taqman real-time RT-PCR." (PMID 25853628, 2015). "KRAS was wild-type in all 4 colon cancer patients but BRAF V600E was detected in two of the 4 cases." (PMID 26375439, 2015). "The present study revealed that tumour dissemination is less likely to occur in colon cancer patients displaying MSI or BRAF mutation, whereas the presence of a KRAS mutation increases the likelihood of disseminated disease." (PMID 25884297, 2015).